IL6 (interleukin 6)
Diseases named in the same sentence as IL6 in open-access papers (continued):
Sharing a sentence is not in itself a finding about the gene and the disease.
vitamin D deficiency (continued). "The analysis of serum level of inflammatory markers reveals mean IL-6 level (in pg/mL) of 19.34 ± 6.17 in patients with vitamin D deficiency (serum Serum 25 (OH)D < 20 ng/mL) and 12.18 ± 4.29 in patients with normal vitamin D level, the difference was found to be statistically significant." (PMID 33214648, 2020). "Moreover, females with severe vitamin D deficiency (≤15 ng/mL) at baseline had higher levels of IL-6 throughout the whole course of recovery after hip fracture than females with 25-OH-D >15 ng/mL." (PMID 27043616, 2016). "For example, Itariu and colleagues interestingly found that the inverse association between vitamin D deficiency and systemic inflammation, measured through IL-6 and CRP in serum, is overcome by treatment with n-3 PUFA supplements in severely obese adults, although vitamin D status is unaffected." (PMID 27043616, 2016). "Additionally, we sought to determine whether TNF-α and IL-6 could play a role as mediators of the detrimental effects of vitamin D deficiency in knee and hip osteoarthritis." (PMID 39940305, 2025). "It has been reported that vitamin D deficiency reduces the downregulation of nuclear factor-κB activity, subsequently leading to a pro-inflammatory state, with an increase in pro-inflammatory cytokines IL-6 and TNF-α and a decrease in anti-inflammatory cytokine IL-10." (PMID 39544568, 2024). "Vitamin D deficiency is associated with increased inflammation and it has been shown that vitamin D3 supplementation can inhibit the release of CRP, TNF-α, and IL-6." (PMID 40364117, 2025). "It is noteworthy that elevated levels of inflammatory biomarkers, such as interleukin-6 (IL-6) and tumor necrosis factor alpha (TNF-α), have been observed in patients with both knee osteoarthritis (KOA) and vitamin D deficiency." (PMID 39940305, 2025). "Vitamin D deficiency inhibits osteoblast differentiation and releases inflammatory factors (TNF-α and IL-6), leading to impaired callus formation and accelerated osteolysis around internal fixation." (PMID 40730978, 2025). "Studies have shown that vitamin D deficiency is associated with elevated levels of CRP, IL-6, TNF-α, and MDA and lower levels of TAC, in newly diagnosed T2DM." (PMID 39544568, 2024). "In a randomized clinical trial involving IBS-D patients with vitamin D deficiency, supplementation with 50,000 IU of vitamin D over 9 weeks yielded improvements in IBS symptoms and reduction in serum interleukin-6 (IL-6) concentrations." (PMID 39064795, 2024). "Pro-inflammatory adipokines IL-6 and TNF-α are produced and released when vitamin D deficiency occurs, resulting in an increase in the amount of fat in the body." (PMID 36360622, 2022). "The univariable analysis showed that severe vitamin D deficiency, being male and HbA1c, TG, LDL-C, UACR, IL-6, and TNF-α levels were significantly associated with the risk of painful DPN." (PMID 33777989, 2021). "In univariate logistic regression models, higher levels of D-dimer, IL-6, and TNF-α were also associated with vitamin D deficiency." (PMID 28464004, 2017). "Vitamin D insufficiency (HF+LVD) significantly exacerbated HF-increased serum concentrations of IL-6 and TNFα by 2.73- and 1.56-fold, respectively." (PMID 28353634, 2017). "In univariate analysis, we demonstrated an association of D-dimer, IL-6 and TNF-α with vitamin D deficiency, suggesting a relationship between vitamin D and inflammation." (PMID 28464004, 2017). "Recent data have shown that severe vitamin D deficiency is associated with an increased risk of human immunodeficiency virus (HIV) disease progression and death, as well as elevated levels of interleukin-6 (IL-6), a biomarker of innate immune activation." (PMID 28464004, 2017). "Moreover, OA patients with vitamin D deficiency showed significantly higher levels of TNF-α and IL-6 (p < 0.05, Mann−Whitney test)." (PMID 39940305, 2025). "Severe vitamin D deficiency associated with increased TNF-α and IL-6 levels in painful DPN group." (PMID 38179375, 2023).
vitamin D deficiency (continued). "The possibility that vitamin D deficiency increases disease severity amongst some patients infected with SARS- CoV-2 is also biologically plausible, given the known association between vitamin D deficiency and elevated serum interleukin 6 (IL-6)." (PMID 35308241, 2022). "IL-6 levels are higher in patients with severe vitamin D deficiency but this data do not reach statistical significance." (PMID 32772324, 2021). "But vitamin D deficiency is associated with an exacerbation of Th1 immune response, resulting in the upregulation of the expression and production of several proinflammatory cytokines including TNF-α, IL-1β, IL-6, and IL-8, too." (PMID 29200598, 2017). "Vitamin D deficiency, independent of dietary fat, increased hepatic fat accumulation in both sexes (p = 0.003), although did not increase hepatic expression of interleukin-6 (p = 0.92) or tumor necrosis factor-α (p = 0.78)." (PMID 28880231, 2017). "The available data suggest that poor nutritional status and vitamin D deficiency might be associated with increased levels of proinflammatory factors, such as TNF-α, IL-6, and CRP." (PMID 27274758, 2016). "Elevated IL-6 values and vitamin D deficiency did not affect the positive effects of resistance training on muscle power and physical function." (PMID 24800209, 2014). "Inflammatory cytokines (IL-6, IL-10, CRP, etc) are elevated in Vitamin D deficiency." (PMID 27417476, 2014). "Vitamin D deficiency significantly enhanced the basal expression of IL-1β, IL-6, and TNF-α in the lungs of mice, while did not influence the basal expression of CXCL1 and CCL3." (PMID 24926881, 2014). "Furthermore, the multivariate logistic analysis indicated a negative correlation between severe vitamin D deficiency and levels of IL-6 (r = −0.56, p < 0.01) and TNF-α (r = −0.47, p < 0.01)." (PMID 39408723, 2024). "Thus, in patients with vitamin D deficiency, the combined effect of elevated TNF-α and IL-6 levels and increased release of adhesion molecules could lead to a further increase in PLT activation and aggregation." (PMID 34576172, 2021). "On the contrary, a similar trial with mildly-moderately affected patients with vitamin D insufficiency reached statistical significance in all (N/L ratio, CRP, LDH, IL6, Ferritin) measured markers." (PMID 35330419, 2022). "The obtained results showed a negative significant correlation between the vitamin D deficiency degree and the IL-6 and CRP concentrations, the IL-6 to IL-10 ratio was disturbed as well." (PMID 33788019, 2021). "We found that the inflammatory markers, comprising hs-CRP and inflammatory cytokines (IL-1 beta, IL-6, and TNF-alpha), were similar between hemodialysis patients with and without vitamin D deficiency." (PMID 32371900, 2020). "The results showed that the levels of TNF-alpha, IL-1 beta, IL-6, and hs-CRP were not connected with vitamin D deficiency." (PMID 32371900, 2020). "Baseline serum levels of IL-6 and soluble CD14, but not of I-FABP, were significantly higher in patients with severe vitamin D deficiency at baseline compared to patients without severe vitamin D deficiency." (PMID 30408125, 2018). "On the other hand, adjustment for resistin, IL-6, MCP-1 and TNF-α did not weaken the relationship between vitamin D deficiency and low CD4 counts." (PMID 24058636, 2013). "As observed previously with higher doses of OVA/Alum, vitamin D deficiency enhanced the capacity of ADLN cells to proliferate and secrete cytokines like IL-4, IL-5, IL-10 (data not shown), but not IL-6, IL-17, TNF or IFNγ (data not shown)." (PMID 23826346, 2013). "In patients with the optimal vitamin D levels (30–100 ng/mL), CRP, IL-6 and erythrocyte sedimentation rate (ESR) were 8.21±0.57, 12.08±0.55 pg/mL and 18.29±4.21 mm/hour, respectively; in other words, they were 19.4%, 27.2% and 52% lower than in patients with vitamin D insufficiency (p<0.05)." (PMID 37558268, 2023).
vitamin D deficiency (continued). "The inflammation markers, including interleukin (IL)−1 beta, IL-6, tumor necrosis factor (TNF)-alpha, and, high-sensitivity C-reactive protein (hs-CRP) were also not significantly different between the study patients with and without vitamin D deficiency." (PMID 32371900, 2020). "Of note, serum levels of C-reactive protein, IL-6 and soluble CD14 were significantly higher in patients with versus without severe vitamin D deficiency, and serum levels of soluble CD14 levels declined in patients with de novo supplementation of vitamin D (median 2.15 vs. 1.87 ng/mL, P = 0.002)." (PMID 30408125, 2018).
autism (108 papers, 2010 to 2025). Persistent deficits in social interaction and communication and interaction as well as a markedly restricted repertoire of activity and interest as well as repetitive patterns of behavior. "IL-6 also impacts neurotransmitter systems like dopamine and serotonin, which have been linked to behaviour and clinical symptoms in autism." (PMID 40002751, 2025). "This study aimed to evaluate the association between CMV IgG levels and IL-6 and IL-1β cytokine profiles in children with autism aged 2–5 years to assess their correlation with autistic behaviours in the high-burden CMV region." (PMID 40002751, 2025). "Here we confirm the link between suicidality and autism and provide more evidence regarding the association of suicidality with increased homocysteine (0.278) and IL-6 (0.487) levels and decreased tryptophan (−0.132) and kynurenic acid (−0.253) ones." (PMID 37371695, 2023). "High levels of IL-6 and IL-1β have been also associated with more severe behavioural deficits in children with autism, while high levels of the anti-inflammatory marker IL-10 have been found in individuals with mild autism-related behavioural impairments." (PMID 36451209, 2022). "The main mechanisms underlying the role of these cytokines in autism pathology include IL-1β stimulation of IL-6 production as the main effector of microglial activation after an infection or injury." (PMID 35328471, 2022). "IL6 has been linked to the pathogenesis of autism since it is involved in the homeostasis between neuro- and gliogenesis and is synergistically induced by xenobiotics, the kynurenine pathway and by the Aryl Hydrocarbon Receptor (AHR)." (PMID 31578139, 2019). "For instance, changes in genes of the complement pathway can affect the process of synapse tagging and removal; and induction of cytokine production such as IL-6 is evidently linked to dendritic spine abnormalities as well as behaviors relevant to autism." (PMID 31200759, 2019). "Especially the cytokine Interleukin-6 (IL-6) has been proposed as a biomarker for autism and was shown to be mechanistically linked to the development of autistic behaviors in mice." (PMID 31052177, 2019). "Biomarkers linked to autism and/or pioglitazone were also studied to attempt to understand the mechanisms involved, namely, IL-6, TNF-alpha, MCP-1, insulin, and leptin." (PMID 29791472, 2018). "Neuroimmune biomarkers linked to autism and/or pioglitazone, namely, IL-6, tumor necrosis factor (TNF)-alpha, monocyte chemotactic protein (MCP)-1/CCL2, insulin, and leptin, were also studied." (PMID 29791472, 2018). "An elevated cytokine response is associated with autism and IL-6 has been repeatedly found to be increased in the autistic brain." (PMID 21595886, 2011). "IL-6 and IL-1β are proinflammatory cytokines commonly linked to the pathophysiology of autism and may affect autistic behaviour." (PMID 40002751, 2025). "Although the cause of autism is not well known, elevated levels of maternal IL-6 linked to prenatal maternal stress may contribute to the risk of autism in humans." (PMID 39553377, 2024). "It was reported that a single injection of IL-6 into pregnant mice led to autism-relevant behaviors in the offspring, while blockade of IL-6 trans-signaling in the brain of mice could cause improved autism-like behavioral symptoms." (PMID 37139330, 2023). "IL-6 signaling is also involved in the maternal immune system activation associated with autism." (PMID 35334937, 2022). "This was contrary to expectation given studies such as one examining children with 22q11 deletion syndrome (at high risk of autism) that found that level of IL-1β in the blood, and the ratio of IL-6:IL10 in serum was significantly associated with social scores on the ADI-R." (PMID 30498564, 2018). "However, elevatedcytokine response is associated with autism and IL-6 has been repeatedly found to beincreased in the autistic brain." (PMID 27942501, 2016).
autism (continued). "Our results provide further evidence for an association of aberrant IL-6 expression with autism." (PMID 21595886, 2011). "Impaired neural cell adhesion and migration, as well as the excessive formation of excitatory synapses caused by elevated IL-6 expression could be an underlying cellular mechanism partially responsible for the pathogenesis of autism." (PMID 21595886, 2011). "The convergent cytokine profiles between Long COVID and autism, particularly sustained elevation of IL-6 and TNF-α with concurrent IL-10 deficiency, provide biological plausibility for shared pathogenic mechanisms that could affect neurodevelopment through neuroinflammation." (PMID 40843696, 2025). "Elevated levels of IL-6 and IL-1β play a crucial role in regulating immune responses and are frequently linked to chronic inflammation, which may affect brain development and behaviour in children with autism." (PMID 40002751, 2025). "Our results provide further evidence that aberrant IL-6 may be associated with autism." (PMID 21595886, 2011). "Blocking IL-6 trans-signaling improves sociability in BTBR T+Itpr3tf (BTBR) autism model mice, likely through enhanced cortical glutamate release, while cerebral IL-6 infusion impairs NMDA receptor-mediated synaptic currents and learning." (PMID 41292555, 2025). "Multiple meta-analyses have investigated the involvement of IL-6 and IL-1β in autism, revealing that increased levels of these cytokines correlate with heightened autism symptom severity, especially in social communication and repetitive behaviours." (PMID 40002751, 2025). "In various studies, TNF‐α, IL‐1β, and IL‐6 levels were found to be higher in autism groups compared to controls." (PMID 39401991, 2025). "They reported that the consumption of an omega-3-enriched diet during gestation and lactation improved brain IL-6 levels in a maternal high-fat diet-induced autism model." (PMID 40906373, 2025). "Research indicates that children with autism exhibit elevated levels of pro-inflammatory cytokines, including interleukin-6 (IL-6) and interleukin-1 beta (IL-1β), alongside reduced levels of anti-inflammatory cytokines, such as interleukin-10 (IL-10)." (PMID 40002751, 2025). "This suggests that CMV’s influence on IL-6 cytokine activity occurs exclusively in children with autism." (PMID 40002751, 2025). "The results show that, within the ASD group, the subscales of food refusal, autism characteristics, and limited variety display a correlation with IL-6 and IL-1β." (PMID 40002751, 2025). "Key cytokines and their receptors investigated in relation to childhood autism include IL-17 A, IL-1β, IL-2R, IL-4, IL-6, and various interleukins, each with diverse cellular origins and target cell types." (PMID 38475688, 2024). "Sachdeva al. demonstrated that curcumin showed beneficial effects in valproic acid-induced-autism in rats by decreasing the IL-6 level." (PMID 36672623, 2023). "In a mouse model, luteolin inhibited IL-6 release from activated microglia and reduced maternal IL-6-induced autism-like behavioral deficits related to social interaction." (PMID 37763703, 2023). "Ahmed Nadeem and colleagues revealed that dysregulation in IL-6 receptors is associated with upregulated IL-17A-related signaling in children with autism, and the IL-6/IL-17A-related parameters are positively correlated with disease severity." (PMID 37139330, 2023). "We found that compared with controls, in subjects with autism, cytokines IL-6, IL-17, TNF-α, and IL-1β increased in the plasma and serum." (PMID 36268027, 2022). "As for autism, many studies indicated that levels of brain cytokines, including IL-6 and IL-1β, were significantly higher in autistic children compared with TD controls." (PMID 36082034, 2022). "For example, several studies have identified a correlation between abnormal levels of several cytokines in neonatal bloodspots, such as IL-1β, IL-6, IL-8, and RANTES, and increased risk of developing autism." (PMID 36268027, 2022).